GSTA1 (glutathione S-transferase alpha 1)
Diseases named in the same sentence as GSTA1 in open-access papers (continued):
Sharing a sentence is not in itself a finding about the gene and the disease.
gastric cancer (2 papers, 2012 to 2014). A primary or metastatic malignant neoplasm involving the stomach. "Namely, homozygous wild-type GSTA1 genotype is associated with an increased risk of gastric cancer in Vietnamese patients." (PMID 24423050, 2014). "Moreover, 17 of the identified genes (CLDN4SRIMYCPRKDCSLPILAPTM4BMYBL2YWHABYWHAZMCM3SERPINE1SLC29A1ID1CDK6EIF2C2PTK2, and GSTA1) have previously been implicated in gastric cancer, and six of the genes (MYCSBDSCHCHD7TOP1COX6C, and CDK6) are included in the Cancer Gene Census." (PMID 22559327, 2012).
glioma (2 papers, 2022 to 2023). A benign or malignant brain and spinal cord tumor that arises from glial cells (astrocytes, oligodendrocytes, ependymal cells). "Wnt signaling pathway, pathways in cancer, glioma, regulation of actin cytoskeleton, tight junction, and basal cell carcinoma were significantly enriched in the GSTA1 high-expressed phenotype." (PMID 36896338, 2023).
heart failure (2 papers, 2020 to 2021). Inability of the heart to pump blood at an adequate rate to meet tissue metabolic requirements. "In this study, Gsta1/4, Gstm1/2, and Gstp1GSTs all showed a significant upward trend, demonstrating that doxorubicin-induced heart failure has a strong correlation with oxidative stress." (PMID 33362553, 2020).
hemorrhagic cystitis (2 papers, 2017 to 2022). Inflammation of the bladder resulting in bloody urine. "BU exposure was significantly associated with aGvHD, TRT and hemorrhagic cystitis and was further analyzed together with genotypes/diplotypes in a multivariate model in which both variables remained significant predictors of respective outcomes (GSTA1, p = 0.003, GSTM1, p = 0.005, Css p ≤ 0.05." (PMID 29207608, 2017).
Hepatic steatosis (2 papers, 2020 to 2024). Steatosis is a term used to denote lipid accumulation within hepatocytes. "Similarly, bicyclol stimulated the expression of GSTA1, thereby reducing hepatic steatosis, suggesting that GSTA1 may be a good target for the discovery of drug candidates against MASLD." (PMID 38791126, 2024). "In conclusion, our results indicate that maintenance of hepatic GSTA1 levels leads to a decrease in FABP1 levels, thereby improving hepatic steatosis, which represents an interesting approach for exploring GSTA1 stabilizers or enhancers as a new class of drugs against MASLD in the future." (PMID 38791126, 2024).
lupus nephritis (2 papers, 2017 to 2023). Glomerulonephritis in the context of systemic lupus erythematosus. "An association between GSTA1 and Cy-PK was also described in patients with lupus nephritis, with poorer response rate in GSTA1*A*A." (PMID 37085674, 2023). "Interestingly in lupus nephritis patients, GSTA1*B genotypes have higher exposure to activated cyclophosphamide metabolites." (PMID 29207608, 2017).
radiation dermatitis (2 papers, 2024 to 2025). "Genotyping of single nucleotide polymorphisms (GSTA1 rs3957356-CT, MAT1A rs2282367-GG) may be linked to the degree of pruritus in radiation dermatitis." (PMID 38814489, 2024). "The reason may be that symptoms of radiodermatitis itchiness are associated with serine proteases (e.g. KLK, matriptase, prostaglandins, or trypsin-like enzymes) and single nucleotide polymorphism genotyping (GSTA1 rs3957356-CT, MAT1A rs2282367-GG)." (PMID 40768536, 2025).
steatosis (2 papers, 2024 to 2026). Increased lipid within the cytoplasm of cells. "In this study, we found that GSTA1 was negatively associated with the accumulation of LD and that overexpression of GSTA1 significantly protected hepatocytes from the progression of steatosis." (PMID 38791126, 2024). "GSTA1 reduces hepatic triglyceride accumulation and mitigates steatosis, suggesting a potential interplay with HDL." (PMID 41512839, 2026). "Overexpression of GSTA1 significantly alleviated steatosis induced by oleic acid (OA) in hepatocytes or a high-fat diet (HFD) in the mouse liver." (PMID 38791126, 2024). "The hepatoprotective and anti-inflammatory drug bicyclol also attenuated steatosis by upregulating GSTA1 expression." (PMID 38791126, 2024). "Overexpression of GSTA1 significantly attenuated oleic acid-induced steatosis in hepatocytes or high-fat diet-induced steatosis in the mouse liver." (PMID 38791126, 2024). "Histopathological analysis further revealed that high expression of GSTA1 in mouse livers (GSTA1) reduced steatosis, hepatocellular ballooning, and lobular inflammation, which was confirmed by the decreased NAS score." (PMID 38791126, 2024). "Importantly, siRNA specifically targeting GSTA1 reduced the inhibitory effect of bicyclol on TG level, indicating the critical role of GSTA1 in mediating the anti-steatosis effect of bicyclol." (PMID 38791126, 2024). "In addition, the hepatoprotective and anti-inflammatory drug bicyclol (Bic) attenuated steatosis by upregulating GSTA1 expression." (PMID 38791126, 2024).
anemia (1 paper, 2018). A reduction in the number of red blood cells, the amount of hemoglobin, and/or the volume of packed red blood cells. "Besides, several targets such as CA2, HMOX1, GSTA1, and NOS2 were closely associated with anemia, which could exhibit significant influences on the therapeutic effects of XSHG." (PMID 29551975, 2018).
atherosclerosis (1 paper, 2023). A disease characterized by the build-up of fatty material and calcium deposition in the arterial wall resulting in partial or complete occlusion of the arterial lumen. "The results of RNA sequencing analysis showed that many antioxidant genes were enriched in Fluid shear stress and atherosclerosis pathway, including MGST1, GSTM3, GSTA1, SOD2 and GSTA4." (PMID 36978937, 2023).
autism (1 paper, 2021). Persistent deficits in social interaction and communication and interaction as well as a markedly restricted repertoire of activity and interest as well as repetitive patterns of behavior. "Interestingly, if there is already a predisposition for ASD, and the child with the GSTA1*CC genotype was exposed to medication during pregnancy, then it leads to the later recognition of autism." (PMID 34248709, 2021).
clear cell renal cell carcinoma (1 paper, 2022). "Interestingly, there is a similar case showing a synergistic effect from the alleles of GSTM1-null, GSTT1-present, GSTA1/T (low activity), and GSTP1/G (low activity) on promoting risk for clear cell renal cell carcinoma." (PMID 35572141, 2022).
Cognitive impairment (1 paper, 2022). Abnormal cognition is characterized by deficits in thinking, reasoning, or remembering. "Western blot analysis showed that the upregulation of GSTA1 in the CA1 area and the downregulation of GSTO1 in the hippocampus were linked to cognitive impairment, commonly seen in aging animals." (PMID 35767571, 2022).
colon cancer (1 paper, 2012). "We also examined GSTA1 expression in Caco-2 cells following exposure to different concentrations of NaB, a short chain fatty acid, that induces differentiation and apoptosis in colon cancer cell lines." (PMID 23251616, 2012).
dyslipidaemia (1 paper, 2025). "Our study confirmed key proteins (PCSK9, ANGPTL3, LPA), identified potential novel targets (GSTA1, GSTA3, EPPK1, PECR, and PLA2G15), and strengthened evidence for CELSR2 and GAS6 in dyslipidaemia." (PMID 40689090, 2025).
endothelial dysfunction (1 paper, 2019). In vascular diseases, endothelial dysfunction is a systemic pathological state of the endothelium (the inner lining of blood vessels) and can be broadly defined as an imbalance between vasodilating and vasoconstricting substances produced by (or acting on) the endothelium. "To take further insight into molecular mechanisms and potential consequences of GSTP1 and GSTA1 polymorphisms with respect to CAD-related HF, we correlated the GSTP1 and GSTA1 variant genotypes with both the indices of heart remodeling and parameters of endothelial dysfunction." (PMID 31275451, 2019).
epilepsy (1 paper, 2021). A brain disorder characterized by episodes of abnormally increased neuronal discharge resulting in transient episodes of sensory or motor neurological dysfunction, or psychic dysfunction. "As already mentioned, a higher risk of epilepsy has been shown in GSTT1-null carriers, while another study showed that GSTA1*CC/GSTT1-null carriers had the greatest risk of developing PME." (PMID 34248709, 2021).
Erythema (1 paper, 2011). Redness of the skin, caused by hyperemia of the capillaries in the lower layers of the skin. "While, the association between the polymorphic variant mut/het of XRCC1 Arg194Trp or wt of GSTA1 results in a higher risk of erythema (OR = 6.01; 95% CI, 1.16-61.04)." (PMID 21749698, 2011). "The mean dose to whole breast(p = 0.002), the presence of either mut/het XRCC1Arg194Trp or wt XRCC3Thr241Met (p = 0.006) and the presence of either mut/het XRCC1Arg194Trp or wt GSTA1(p = 0.031) were confirmed as predictors of radiotherapy-induced erythema by MVA." (PMID 21749698, 2011). "In addition, a high rate of erythema was correlated with the mut/het of XRCC1 Arg194Trp or with of the wt GSTA1, while a trend toward having a protective factor was observed when a mut/het of XRCC1 Arg194Trp or the wt XRCC1 Arg399Gln alleles were expressed." (PMID 21749698, 2011).
head-neck squamous cell carcinoma (1 paper, 2022). "The expression level of GSTA1 was decreased in most tumors, with significant decreases in GBM, BRCA, CHOL, COAD, head-neck squamous cell carcinoma (HNSC), and several other cancer types." (PMID 36291099, 2022).
iron overload (1 paper, 2024). "Recent studies have demonstrated that GSTA1-mediated ROS and Ca2+ signaling pathways are mainly implicated in the enhancement of aldosterone secretion, and low-activity of GSTA1 is associated with iron overload-induced kidney injury." (PMID 38961491, 2024).
leukemia (1 paper, 2021). A malignant (clonal) hematologic disorder, involving hematopoietic stem cells and characterized by the presence of primitive or atypical myeloid or lymphoid cells in the bone marrow and the blood. "GSTA1 mediates cisplatin in some solid cancer cells and imatinib in leukemia cells." (PMID 34209254, 2021).
lung adenocarcinoma (1 paper, 2023). A carcinoma that arises from the lung and is characterized by the presence of malignant glandular epithelial cells. "Among them, low expression of C12orf56, DLX5, DSC3, FEZF1, GSTA1, H2BC9, IGSF11 and high expression of EREG, CEACAM6, SLC34A2 in lung adenocarcinoma were found to predict poor prognosis for patients." (PMID 37035196, 2023).
lymph node metastasis (1 paper, 2010). "The AORs with their 95% CIs of GSTP1 and GSTA1 gene polymorphisms on the clinico-pathological characteristics, such as clinical stage, tumor size, lymph node metastasis, distant metastasis, and Child-Pugh grade in HCC patients were also estimated." (PMID 20331903, 2010).
memory impairment (1 paper, 2022). "Opposite to the down-regulation of GSTA1, GSTO1, and KEAP1, the BACE1 and MAOA proteins are elevated during the aging-associated memory impairment." (PMID 35767571, 2022).
myocardial infarction (1 paper, 2014). Gross necrosis of the myocardium, as a result of interruption of the blood supply to the area, as in coronary thrombosis. "The effect of GSTM1, GSTT1, GSTP1 and GSTA1 gene polymorphisms on predicting overall and specific cardiovascular outcomes (myocardial infarction, MI or stroke) was analyzed using Cox regression model, and differences in survival were determined by Kaplan-Meier." (PMID 24423050, 2014). "This study examined the association between the deletion polymorphisms in GSTM1 and GSTT1 as well as SNPs in GSTA1 (rs3957357) and GSTP1 (rs1695) genes with overall and cardiovascular mortality as well as the death from myocardial infarction (MI) and stroke (CVI) in 199 dialysis patients." (PMID 24423050, 2014).
osteoarthritis (1 paper, 2019). A noninflammatory degenerative joint disease occurring chiefly in older persons, characterized by degeneration of the articular cartilage, hypertrophy of bone at the margins and changes in the synovial membrane. "In this study, we evaluated the effects of treatment with A-ITC and P-ITC on the protein levels of the antioxidant enzymes HO-1, NQO1, GSTM1, and GSTA1 in the hippocampus of animals with osteoarthritis pain." (PMID 31905764, 2019).
pterygium (1 paper, 2024). A wedge-shaped fibrovascular lesion arising from the bulbar conjunctiva and extending to the cornea. "As the NESs of the antioxidant and cytokines/chemokines indicated their positive enrichment in pterygiums in both Asian and European samples, GSTA1, PARL, and FOS might contribute to their upregulation in response to oxidative stress and DNA damage." (PMID 38732006, 2024).
renal cell carcinoma (1 paper, 2025). "It was shown that renal cell carcinoma (RCC) patients’ urine EVs included lower levels of mRNA for pterin-4 alpha-carbinolamine dehydratase-1 (PCBD1), glutathione transferase alpha 1 (GSTA1), and CCAAT enhancer binding protein alpha (CEBPA) than controls." (PMID 40305328, 2025).
skin cutaneous melanoma (1 paper, 2022). "Similar to GSTZ1, high levels of GSTA1 were positively associated with higher OS and DFS in patients with ACC and were potentially associated with prolonged DFS in patients with LUSC, but levels of GSTA1 were only negatively correlated with OS in patients with skin cutaneous melanoma (SKCM)." (PMID 36291099, 2022).
Stroke (1 paper, 2014). Sudden impairment of blood flow to a part of the brain due to occlusion or rupture of an artery to the brain. "Specifically, dialysis patients who were homozygous for both GSTM1*0 and GSTA1*A alleles exhibited a HR of 4.38 (95%CI:1.50-12.75, P = 0.007) for stroke in comparison with carriers of at least one GSTM1-active and/or GSTA1*B allele." (PMID 24423050, 2014). "Homozygous carriers of combined GSTM1*0/GSTA1*A genotype exhibited significantly shorter time to death of stroke or MI in comparison with carriers of either GSTM1-active or at least one GSTA1*B gene variant." (PMID 24423050, 2014). "Homozygous carriers of combined GSTM1*0/GSTA1*A genotype exhibited significantly shorter time to MI or stroke in comparison to ESRD patients carriers of either GSTM1-active or GSTA1*B gene variant." (PMID 24423050, 2014). "The borderline effect modification by wild-type GSTA1*A/*A genotype on associations between GSTM1-null and analyzed outcomes was found only for death from stroke." (PMID 24423050, 2014). "The significant effect modification by GSTA1*A/A genotype on associations between GSTM1-null and analyzed outcomes was found only for the death from stroke." (PMID 24423050, 2014). "Moreover, statistically significant interactive effect existed between GSTM1-null and the GSTA1*A/*A genotype for death of stroke." (PMID 24423050, 2014). "However, patients homozygous for GSTA1*A allele demonstrated a non-statistically significant HRs of 1.73, 1.87 and 2.52 for cardiovascular mortality, MI and stroke, respectively." (PMID 24423050, 2014). "The interpretation of our results on effect modification by GSTA1*A/A genotype in GSTM1*0/0 individuals regarding the death from MI and stroke should be in the light of the fact that ESRD patients exhibit powerful oxidant stress, and therefore a strong Nrf mediated induction of GST expression." (PMID 24423050, 2014).
thalassemia (1 paper, 2024). An inherited blood disorder characterized by a decreased synthesis of one of the polypeptide chains that form hemoglobin. "The influence of treosulfan and S, S-EBDM exposure, and GSTA1/NQO1 polymorphisms on graft rejection, RRTs, chimerism status, and 1-year overall survival (OS), and thalassemia-free survival (TFS) were assessed." (PMID 37846495, 2024).
type 1 diabetes (1 paper, 2024). "High GSTA1 levels were associated with elevated markers of systemic inflammation in the urine of juvenile type 1 diabetes." (PMID 39541108, 2024).
cancer (27 papers, 2012 to 2025). A tumor composed of atypical neoplastic, often pleomorphic cells that invade other tissues. "GSTA1 gene which encodes for GSTα protein has been linked to various aspects of cancer namely, proliferation, metastasis and drug resistance." (PMID 32405336, 2020). "When considering GSTA1 polymorphisms, those linked to a reduced expression of the GSTA1 enzyme may result in an accumulation of carcinogens in the body, thereby elevating cancer risk." (PMID 39063019, 2024). "Mutations in GSTA1 could feasibly alter the binding affinity of glutathione to carcinogenic compounds, leading to variation in cancer susceptibility." (PMID 36344807, 2022). "GSTZ1 and GSTA1 have also been found to be associated with various forms of cancer." (PMID 36291099, 2022). "Multiple inhibitors of GST class proteins have been found and created which inhibits the activity of most of the GST enzymes, but till date only few compounds have shown to exhibit specific inhibition against GSTA1 which amongst all GSTs have been linked most to cancer progression." (PMID 32405336, 2020). "For example, expression differences in DMET genes such as CYP3A4, CYP2A6 and GSTA1 may be associated with cancer risks." (PMID 29177108, 2012). "Therefore, the downregulation of the GSTA1 mRNA expression caused by all tested prenylflavonoids in proliferating CaCo-2 cells observed in this study can be considered as positive regarding the suppression of cancer cell proliferation." (PMID 32708388, 2020). "In High 2 or Basal groups, downregulation of GSTA1, GSTM1, GSTM2, and GSTT1 gene expression can be correlated with the impaired ability to eliminate carcinogenic compounds and increased cancer risk." (PMID 40426890, 2025). "GSTA1 is a critical factor in cancer progression and is expressed abundantly in most human tumors and tumor cell lines." (PMID 37047688, 2023). "The main SNP type of GSTA1 found in most cancers were amplification, while in some other cancer type, such as UCEC and COAD, the main SNP type found was mutation." (PMID 36291099, 2022). "Namely, synthetic bombesin-sulphonamide derivatives are able to recognize bombesin receptor on cancer cell thus increasing drug uptake, which, once in the cell, undergoes GSTA1-1 catalyzed modification into GST competitive inhibitor." (PMID 30487385, 2018). "A clearer understanding of the role of GSTA1 expression in modulation of transitioning between cellular states has important implications in diseases such as cancer in which there is an imbalance in cellular proliferation, differentiation and apoptosis." (PMID 23251616, 2012). "Additionally, GSTA1 has been shown to influence cancer cell viability, EMT processes, adhesion, invasion, and metastasis." (PMID 37047688, 2023). "A specific pro-drug has been identified even for cancer cells with upregulated GSTA1-1 expression." (PMID 30487385, 2018). "The increased expression of GSTA1 can reduce the proliferation of cancer cells and protect cells against the damage of lipid peroxidation, which has been an important mechanism of anti-oxidative stress in detoxification of toxic substances and reactive oxygen species." (PMID 30254584, 2018). "Both GSTA2 and GSTA1 (which is 28 kb downstream to GSTA2), have been shown to have important roles in catalyzing carcinogenic substrates and nucleotide variation in them has been shown to be associated with cancer." (PMID 25275310, 2014). "To finesse this approach to target particular GST isoforms in the context of cancer, here we have determined the kcat/Km for the human isoforms of GSTK1-1, GSTA1-1 and GSTA4-4 with respect to GSH and CDNB." (PMID 38593670, 2024). "GSTK1-1 is the main GST isoform in the mitochondrial matrix, but the GSTA1-1 and GSTA4-4 isoforms are also thought to be in the mitochondria with their distribution altering in transformed cells, thus potentially providing a cancer specific target." (PMID 38593670, 2024).